INS (insulin)
Diseases named in the same sentence as INS in open-access papers (continued):
Sharing a sentence is not in itself a finding about the gene and the disease.
Glucose intolerance (continued). "Further, there was a significant increase in the body weight (P < 0.01), glucose intolerance, area under the curve for glucose, serum insulin level (P < .001) and HOMA-IR index of letrozole treated group as compared to the CMC control group." (PMID 29642911, 2018). "We also demonstrated that UC-MSCs repaired the glucose intolerance by suppressing inflammatory mediator release in insulin target tissues of the T2D animal model." (PMID 29096724, 2017). "The different Wfs1 mutant mice that have currently been created show glucose intolerance and diminished insulin secretion." (PMID 28860598, 2017). "Founder HH induced glucose intolerance, insulin insensitivity, and hyperlipidaemia in male offspring (p < 0.05)." (PMID 28208792, 2017). "ATV- and SQV-induce glucose intolerance, reduce insulin secretion and impair insulin signaling in rat skeletal muscles." (PMID 29121676, 2017). "SFRP4 treatment resulted in a decrease in insulin secretion and glucose intolerance, while silencing of SFRP4 led to glucose-stimulated insulin release." (PMID 29037197, 2017). "We show that impairment of insulin secretion is the most important factor to predict glucose intolerance in NAFLD." (PMID 28878826, 2017). "Here we show that deletion of Raptor, which is an essential component of mTORC1, in insulin-expressing cells promotes hypoinsulinemia and glucose intolerance." (PMID 28598424, 2017). "As expected, maternal and post-weaning HFD induced glucose intolerance and increased plasma insulin levels." (PMID 29118320, 2017). "This study establishes that impairment of insulin secretion is the most important factor to predict glucose intolerance in Japanese patients with NAFLD." (PMID 28878826, 2017). "GLP-1 receptor knockout mice (GLP-1r−/−) show glucose intolerance and reduced insulin secretion after a glucose load." (PMID 28185153, 2017). "Significantly higher glucose and insulin in the BL session suggests glucose intolerance and insulin insensitivity." (PMID 28270559, 2017). "Alterations in the adipose tissue (endocrine organ), the gut incretin-system (enteroinsular axis), renal reabsorption of glucose, and brain insulin response also play important roles in the development of glucose intolerance and type 2 DM." (PMID 29176960, 2017). "Glucose intolerance with increased insulin levels are apparent in FATZO mice as young as 6 weeks of age." (PMID 28640857, 2017). "Overall, this suggests that as a result of paternal programming, male offspring are more prone to glucose intolerance in early life than female offspring, who were able to adapt by increasing insulin production." (PMID 28208792, 2017). "Conditions that prevented the resolution of DM after surgical resection included chronic pancreatitis, long standing DM, insulin use, previous glucose intolerance, and malignancy." (PMID 28272344, 2017). "For example, chronic induction of HO-1 improved insulin sensitivity and glucose intolerance and these benefits were attributed to its anti-inflammatory and adipogenic effects." (PMID 28445528, 2017). "The discrepancy between the adequate insulin response at ZT21 and inadequate response at ZT15 indicates that the observed glucose intolerance at ZT15 is probably due to reduced beta cell sensitivity or an inhibition of insulin release." (PMID 28374068, 2017). "BL at night was associated with significant increases in plasma glucose and insulin suggestive of glucose intolerance and insulin insensitivity." (PMID 28270559, 2017). "SHR-CRP transgenic rats treated with salsalate exhibited reduced serum glucose, significant amelioration of glucose intolerance and higher sensitivity of skeletal muscle to insulin action." (PMID 28586387, 2017). "To examine the role of STAT3 and TLR4 in the development of glucose intolerance, we tested IL-6-induced insulin-stimulated uptake of 2-NBDG in the skeletal muscle." (PMID 28706484, 2017).
Glucose intolerance (continued). "In this case, the offspring of these mothers had a defect in insulin secretion leading to glucose intolerance." (PMID 28574454, 2017). "In particular, it has been demonstrated that baicalein improves hyperglycemia and glucose intolerance, and promotes insulin secretion by inhibiting islet cell apoptosis in streptozotocin-induced diabetic mice." (PMID 28445528, 2017). "This sequence of events eventually resulted in glucose intolerance and impaired insulin secretion in animal models of both types of diabetes." (PMID 28194257, 2017). "WSD induced glucose intolerance and IR as evidenced by an increase in area under the curve (AUC) glucose and AUC insulin values during glucose tolerance tests (GTTs), as well as HOMA-IR and HbA1c levels." (PMID 28545403, 2017). "Such disturbances were accompanied by increased levels of body weight and adiposity, decreased levels of insulin sensitivity, and glucose intolerance." (PMID 29062272, 2017). "In fact, P2rx7−/− mice had increased serum triglyceride and cholesterol levels and displayed glucose intolerance and resistance to insulin." (PMID 29018292, 2017). "Change in the consumption of HFS or HFF to a C diet ameliorated the insulin and glucose intolerance." (PMID 28420148, 2017). "The authors also showed that ceramides/dihydrceramides positively correlate with glucose intolerance and negatively correlate to insulin sensitivity." (PMID 28714882, 2017). "A recent study, using Bama miniature pigs fed with high-fat and high-sucrose diet for 23 months, displays the gradually increasing fasting insulin levels and glucose intolerance along with the lateral-half experimental period." (PMID 29046729, 2017). "Our investigation found that, high fat diet feeding in rats showed significant glucose intolerance and high level of plasma insulin concentration." (PMID 28578702, 2017). "Glucose intolerance as high as 89.7% is found in patients with impaired insulin secretion defined by <43.2 pmol/mmol (40 μU/mg) IGI." (PMID 28878826, 2017). "After 8 weeks of HFD, there was mild but significant increase in AUC from TKO-HFD compared to TKO-ND, suggesting impaired insulin and glucose intolerance." (PMID 28661427, 2017). "Mice with chronic activation of CAMK2 in beta cells developed glucose intolerance and abnormal insulin secretion through a ryanodine receptor 2 (Ryr2) dependent mechanism." (PMID 28777829, 2017). "NMN administration restored β cell glucose-stimulated insulin secretion and hepatic and muscle insulin sensitivity in mouse models of induced glucose intolerance." (PMID 29264533, 2017). "Rate of postpartum glucose intolerance in women who were treated with insulin was 54.4% versus 41.7% in women who had taken metformin while the same rate was 15.4% in diet-only group." (PMID 28491872, 2017). "When comparing other fatty acid levels from baseline with the progression of glucose intolerance in the dogs, only palmitic acid (C16:0) showed a strong positive linear correlation (glucose R2 = 0·891, insulin R2 = 0·818)." (PMID 28332596, 2017). "HFD feeding resulted in significant elevation of fasting glycemia and insulinemia, glucose intolerance, enhanced insulin secretion induced by glucose, and increased BW after 7 weeks when compared to CHD-fed mice." (PMID 28683308, 2017). "Taking these findings together, impairment of insulin secretion is the most important factor to predict glucose intolerance in NAFLD." (PMID 28878826, 2017). "An experimental study that examined genetic disruption of D2R resulted in glucose intolerance with impaired insulin secretion." (PMID 28384295, 2017). "The study investigated the protective effects of naringin on glucose intolerance and impaired insulin secretion and signaling in vivo." (PMID 29121676, 2017). "OC has been reported to regulate glucose metabolism by increasing insulin secretion and improving glucose intolerance." (PMID 28732499, 2017).
Glucose intolerance (continued). "The obese rats used in this study did not exhibit a change in fasting plasma insulin levels but showed an increase in blood glucose and plasma insulin levels after glucose loading, indicating that they are in the initial stage of glucose intolerance." (PMID 28717164, 2017). "This is primarily due to abnormal methylation of the H19-Igf2 locus, which further induces transgenerational glucose intolerance and abnormal insulin levels." (PMID 28814771, 2017). "In another report, high-fat diet mice showed attenuated acute insulin secretion to glucose infusion, poor compensatory islet growth, and glucose intolerance." (PMID 28654680, 2017). "We report herein that C2C12 cells treated with KPC-exosomes have induced insulin and PI3K/Akt signalling inhibition, triggering insulin resistance and glucose intolerance." (PMID 28710412, 2017). "This study, was therefore designed to investigate the potential role of naringin in PI-induced glucose intolerance, impaired insulin secretion and signaling in vivo." (PMID 29121676, 2017). "The results of insulin tolerance and glucose intolerance should be at least partially ascribed to the impaired insulin sensitivity of adipose tissue, since the serum insulin levels are similar between the zinc-supplemented mice and the control mice." (PMID 29057818, 2017). "The third mechanism is leveraging the anti-inflammatory function of probiotics, which improves low-grade inflammation, steatosis, glucose intolerance and insulin sensitivity." (PMID 29090088, 2017). "We have, therefore, included a bout of moderate-intensity exercise before the two trial meals to assess its possible contribution to postprandial glucose intolerance and compensatory insulin response after meals that differ in carbohydrate content." (PMID 27798656, 2016). "The GTT assay suggested that the HFD-fed ASKO mice exhibited glucose intolerance, and the significantly elevated blood glucose content upon insulin administration indicated decreased insulin sensitivity in the HFD-fed ASKO mice." (PMID 27655719, 2016). "In contrast, mice with muscle‐specific Pikfyve disruption have normal lifespan but exhibit early‐age whole‐body glucose intolerance and muscle insulin resistance, thus establishing the key role of muscle PIKfyve in glucose homeostasis." (PMID 27273882, 2016). "Selective deletion of ARNT in beta cell of the pancreas leads to glucose intolerance, impaired insulin secretion and deregulated islet gene expression." (PMID 28005939, 2016). "Abnormal proinsulin accumulates and cannot be converted into insulin, leading to glucose intolerance and type 2 diabetes." (PMID 27974624, 2016). "In oral glucose tolerance test, GK+/−ApoE−/− mice showed significant glucose intolerance and impaired glucose-stimulated insulin secretion." (PMID 27774459, 2016). "Significantly, the accelerated onset of glucose intolerance with elevated insulin levels, cardiac systole deficits, hypertrophy, and ocular cataracts in Mbnl3ΔE2 mice occur largely without DM1-like splice defects in multiple RNAs." (PMID 27484195, 2016). "Together, these results demonstrate that independent of time of day and sleep pressure, short sleep deprivation during the resting phase favors glucose intolerance in rats by attenuating the first‐phase insulin response to a glucose load." (PMID 27354542, 2016). "The simultaneous assessment of insulin sensitivity and beta-cell function allowed us to study metabolic profiles that promote T2D and glucose intolerance." (PMID 27597980, 2016). "It is important to point out that the Arg-II−/− mice are protected from whole body glucose intolerance with improved insulin sensitivity and less NAFLD on HFD." (PMID 27920727, 2016). "This study reproduced the phenomenon of stress-induced glucose intolerance, characterized by higher levels of basal insulin and higher levels of glucose during the GTT." (PMID 27538526, 2016).
Glucose intolerance (continued). "In the liver, the impaired insulin signalling pathway, which involves the insulin receptor substrate (IRS) proteins and AKT cascade, results in insulin insensitivity and glucose intolerance." (PMID 26882989, 2016). "In patients with NAFLD with aberrant glucose metabolism, the insulin sensitivity is impaired in adipose tissue, liver, and muscle, but only adipose tissue glucose intolerance will exacerbate T2DM." (PMID 27563875, 2016). "The remarkable glucose intolerance that developed in βS6KO mice was accompanied by defective insulin secretion, which was observed as significant reduction in insulin and C-peptide levels after glucose load." (PMID 27457971, 2016). "Knock-out of BI-1 in mice exacerbates glucose intolerance and impairs insulin signaling induced by high-fat diet-induced chronic ER stress." (PMID 27576594, 2016). "A circadian influence accounted for 12% of the evening glucose intolerance that was attributed to a 27% reduction in early-phase insulin secretion." (PMID 27798656, 2016). "Accelerated onset of glucose intolerance with elevated insulin levels, cardiac systole deficits, left ventricle hypertrophy, a predictor of a later onset of heart failure and the development of subcapsular and cortical cataracts is observed in Mbnl3ΔE2 mice." (PMID 27484195, 2016). "Loss of function of HID-1 in mice leads to diabetes-like symptoms characterized by glucose intolerance, insufficient insulin release, and elevated proinsulin secretion." (PMID 27751232, 2016). "After only two weeks of diet HCD-fed mice showed enhanced peripheral insulin sensitivity (p < 0.05) and mild glucose intolerance (p < 0.01) when compared to Chow-fed mice." (PMID 27992582, 2016). "Old Wistar rats (24 months) and Sprague-Dawley rats (28 months) display oral glucose intolerance and exhibit a decrease in a glucose-stimulated insulin release compared with young rats (2–4 months)." (PMID 27441644, 2016). "The Oxtr−/− mice fed the high-fat diet exhibited increased apoptosis in pancreatic islets, which results in impaired insulin secretion as well as glucose intolerance." (PMID 27143105, 2016). "Fasted FXR-null mice exhibit impaired glucose intolerance, insulin insensitivity, and increased levels of plasma triglyceride, free fatty acids, and cholesterol." (PMID 27733832, 2016). "Administration of recombinant vaspin improves glucose intolerance, and insulin sensitivity in diet-induced obese mice." (PMID 27383120, 2016). "Unexpectedly, mice fed a high carbohydrate diet displayed enhanced sensitivity to exogenous insulin, despite having mild glucose intolerance and increased liver steatosis." (PMID 27992582, 2016). "In HFD-fed mice, 30-day CAP exposure suppressed insulin-stimulated endothelial nitric oxide synthase (eNOS) phosphorylation in skeletal muscle and increased adipose tissue inflammation and systemic glucose intolerance." (PMID 27128347, 2016). "Current theories of the pathogenesis of glucose intolerance and T2D include a defect in glucose uptake and insulin action in the skeletal muscle and liver as well as disturbed adipocyte functions." (PMID 27323669, 2016). "This latter result implies that rapamycin prevents rimonabant-induced glucose intolerance by increasing insulin sensitivity, as was shown by an ITT." (PMID 26563389, 2016). "Female mice fed WD-C were protected from whole-body glucose intolerance and had better insulin sensitivity compared to mice fed WD-L, similar to the effects observed in male mice." (PMID 26924712, 2016). "Some studies reported that JJ mice display glucose intolerance and reduced insulin secretion when compared to other mouse strains (DBA/2, C3H/HeJ and AKR/J) or NN mice even though these results were not confirmed by others." (PMID 27403868, 2016). "Underdeveloped or defective insulin SGs lead to compromised insulin secretion and glucose intolerance." (PMID 26518685, 2016).
Glucose intolerance (continued). "Inppl1 transgenic mice show impaired insulin signaling and glucose intolerance, while Inppl1 KO mice are highly resistant to weight gain on a high-fat diet." (PMID 27834631, 2016). "This is consistent with previous studies where APP/PSEN1 mice have increased fasted insulin, develop glucose intolerance and become less insulin sensitive when placed on a HFD." (PMID 26916443, 2016). "For example, pioglitazone and metformin, common treatments for glucose intolerance, can enhance insulin sensitivity in patients with NAFLD/NASH; however, other histological features, such as fibrosis, are not significantly influenced." (PMID 27563875, 2016). "Our results show that obesity triggers RIPK3 overexpression in the WAT of mice and humans, where it dampens adipocyte apoptosis and inflammation, thereby preventing impaired insulin signalling as the basis of glucose intolerance." (PMID 27323669, 2016). "When we placed mice on a 60 % HFD, we found that male APP/PSEN1, display evidence of transient elevated fasted plasma insulin as well as both glucose intolerance and insulin insensitivity." (PMID 26916443, 2016). "In type II diabetic KK-Ay mice, AZL-M was superior to candesartan in improving glucose intolerance, insulin sensitivity, and inducing beneficial adipocyte differentiation." (PMID 27536242, 2016). "The aP2-CETPTg mice exhibited glucose intolerance, lower plasma insulin concentrations but increased insulin sensitivity compared with wild type mice." (PMID 26973702, 2016). "Oxtr−/− mice developed normally, but exhibited impaired insulin secretion and showed glucose intolerance under a high-fat diet." (PMID 27143105, 2016). "We have also recently demonstrated the importance of the silencing of another member of this family, the Acyl-CoA thioesterase 7 (Acot7) which β-cell specific overexpression lead to glucose intolerance and impaired insulin secretion in response to glucose." (PMID 28123396, 2016). "Pre-meal exercise exacerbated glucose intolerance with both diets most likely due to impairment of insulin signaling by pre-meal elevation of FFAs." (PMID 27798656, 2016). "It has been shown that a defect in β-cell insulin secretion can be present early, before the development of glucose intolerance, resulting from the toxic effect of iron deposition in the pancreas." (PMID 27872738, 2016). "Pin1 enhances insulin-induced IRS-1 tyrosine phosphorylation through its isomerase activity, and Pin1 knockout mice exhibit impaired insulin signaling with glucose intolerance." (PMID 26074875, 2015). "Here, B2R-/- presented glucose intolerance only when submitted to HFD, but higher sensitivity to insulin after HFD probably caused by the decreased body fat." (PMID 26302153, 2015). "Prevented neuronal diabetic complications such as infarction, neuronal damage, development of post-ischemic glucose intolerance and improved memory and insulin secretion in male ddY mice." (PMID 26404212, 2015). "In summary, this study demonstrates that ELS induced by LN conferred some metabolic protection against insulin and/or glucose intolerance in a diet-dependent manner during adulthood." (PMID 26441828, 2015). "After finding modest but reproducible attenuation of diet-induced glucose intolerance, we assessed insulin sensitivity using hyperinsulinemic-euglyemic clamp and tracer kinetics." (PMID 26393344, 2015). "This increases our understanding of why rapamycin was beneficial to impaired insulin signaling in vitro but further exacerbated glucose intolerance under conditions of inflammatory stress in vivo." (PMID 26449763, 2015). "Here, the beneficial effect of rapamycin on glucose uptake and consumption in vitro was contradictory to the aggravated glucose intolerance and reduced insulin sensitivity observed in vivo under inflammatory stress." (PMID 26449763, 2015). "Both authors interpreted the glucose intolerance as a consequence of chronically elevated serum insulin levels." (PMID 26394692, 2015).